MEX3A (mex-3 RNA binding family member A)
Diseases named in the same sentence as MEX3A in open-access papers (continued):
Sharing a sentence is not in itself a finding about the gene and the disease.
cervical cancer (3 papers, 2021 to 2022). A primary or metastatic malignant neoplasm involving the cervix. "We found higher expression of MEX3A in HPV-negative cervical carcinoma cell lines and tumor tissues." (PMID 33997099, 2021). "Additionally, higher expression of MEX3A and TTYH3 was associated with a shorter overall survival of patients with HPV-negative cervical cancer." (PMID 33997099, 2021). "It has been claimed that MEX3A affects cell proliferation and migration via the EMT pathway in pancreatic and cervical cancers." (PMID 36614043, 2022). "In addition, upregulation of MEX3A was associated with shorter overall survival only in patients with HPV-negative cervical cancer, implying that MEX3A is not only related to the occurrence of HPV-negative cervical but also to prognosis of HPV-negative cervical cancer." (PMID 33997099, 2021). "However, MEX3A was reported to suppress proliferation and EMT by restraining the Akt signaling pathway in cervical cancer." (PMID 35715407, 2022). "In this study, the authors discovered the multiple genes in HPV-negative cervical cancer, including PRAME, HMGA2, ETV4, MEX3A, TM7SF2, SLC19A1, and TTYH3, which could contribute to HPV-negative cervical cancer development." (PMID 33997099, 2021). "Furthermore, high expression of MEX3A and TTYH3 was also related to shorter overall survival of patients with HPV-negative cervical cancer, which confirmed the important prognostic value of MEX3A and TTYH3 expression in patients with HPV-negative cervical cancer." (PMID 33997099, 2021).
hepatocellular carcinoma (3 papers, 2021 to 2024). A malignant tumor that arises from hepatocytes. "MEX3A expression is upregulated in hepatocellular carcinoma (HCC) and corelated with the stage of HCC and high MEX3A protein expression level predicts the poor prognosis of HCC patients." (PMID 34486491, 2021).
osteosarcoma (3 papers, 2021 to 2024). A usually aggressive malignant bone-forming mesenchymal neoplasm, predominantly affecting adolescents and young adults. "Taken together, these findings highlighted the role of MEX3A in osteosarcoma cells on proliferation, apoptosis and cell cycle." (PMID 33827584, 2021). "In conclusion, MEX3A was not only highly expressed in osteosarcoma tissues, but also involved in the regulation of the disease." (PMID 33827584, 2021). "The expression level of MEX3A in osteosarcoma tissues was markedly higher than that in adjacent normal tissues." (PMID 33827584, 2021). "Consistently, we found that MEX3A knockdown induced apoptosis of osteosarcoma cells, resulting in the activation of Caspase-3, Caspase-8 and HSP60." (PMID 33827584, 2021). "On the other hand, the differential expression of MEX3A in osteosarcoma cell lines and control cell line hFOB 1.19 was detected, suggesting that MEX3A was highly expressed in MNNG/HOS and U-2OS." (PMID 33827584, 2021). "Firstly, we determined that expression of MEX3A was significantly higher in osteosarcoma tissues than that in marginal bone by immunohistochemical staining." (PMID 33827584, 2021). "To evaluate expression of MEX3A in osteosarcoma, we analyzed 104 microarray chips of osteosarcoma patients with detailed clinicopathological information." (PMID 33827584, 2021). "In summary, these findings predicated that therapy directed at decreasing MEX3A expression is a potential osteosarcoma treatment." (PMID 33827584, 2021). "The preliminary exploration on the molecular mechanism of MEX3A in osteosarcoma cells showed that the induction of apoptosis needs the participation of a series of apoptosis-associated factors." (PMID 33827584, 2021). "The current study determined that the expression of MEX3A was upregulated in osteosarcoma tissues than that in marginal bone." (PMID 33827584, 2021). "Using in vitro experiments, we proved that the decreased expression of MEX3A has a certain inhibitory effect on the development and progression of osteosarcoma cells." (PMID 33827584, 2021). "Firstly, the difference of MEX3A expression level between osteosarcoma and marginal bone tissue was determined by immunohistochemical staining." (PMID 33827584, 2021). "In this study, we analyzed the expression of MEX3A in osteosarcoma and evaluated its potential role in osteosarcoma." (PMID 33827584, 2021). "Herein, this study was to investigate the correlation between MEX3A and the progression of osteosarcoma." (PMID 33827584, 2021). "Here, we tried to illuminate the relation between MEX3A and osteosarcoma." (PMID 33827584, 2021). "Furthermore, mouse xenograft model confirmed the inhibitory effects of MEX3A knockdown on osteosarcoma formation." (PMID 33827584, 2021). "Albeit these, whether MEX3A was involved in the regulation of osteosarcoma cell function remained elusive." (PMID 33827584, 2021). "Furthermore, mouse xenograft model confirmed inhibitory effects of MEX3A knockdown on osteosarcoma formation." (PMID 33827584, 2021). "Furthermore, mouse xenograft model further supported inhibitory effects of MEX3A knockdown on osteosarcoma formation." (PMID 33827584, 2021). "Whether the downregulation of MEX3A can inhibit the growth of osteosarcoma cells in vivo remains to be further explored." (PMID 33827584, 2021). "Therefore, MEX3A was involved in apoptosis induction of osteosarcoma cells requiring the participation of a series of apoptosis- associated factors." (PMID 33827584, 2021). "Moreover, Transwell assay indicated that the number of MNNG/HOS and U-2OS cells in shMEX3A migrated to lower chamber decreased dramatically, suggesting that the downregulation of MEX3A reduced the migration ability of osteosarcoma cells (P < 0.001)." (PMID 33827584, 2021). "All in all, the inhibition of MEX3A reduced the migration ability of osteosarcoma cells." (PMID 33827584, 2021).
osteosarcoma (continued). "The preliminary exploration on the molecular mechanism of MEX3A in osteosarcoma cells showed that the induction of apoptosis needs the participation of a series of apoptosis- associated factors, such as upregulation of Caspase 3, Caspase 8 and HSP60, downregulation of HSP27 and XIAP." (PMID 33827584, 2021). "MEX3A may be associated with tumors while has not yet seen its coverage on osteosarcoma." (PMID 33827584, 2021).
Ascites (2 papers, 2022 to 2024). Accumulation of fluid in the peritoneal cavity (between the layers of the peritoneum that lines the abdomen). "Meanwhile, the Mex3a promoter methylation level was significantly higher in patients with ascites (median: 0.438% and interquartile range: 0.178%–0.678%) than in those without ascites (median: 0.252%, interquartile range: 0.086%–0.502%, and p = 0.008)." (PMID 39564121, 2024). "At the same time, we observed an inconsistency between the absence of significant associations between mRNA levels of Mex3a PMR and factors such as age, HBV-DNA, and ascites, which may be related to post-transcriptional translation." (PMID 39564121, 2024).
colitis (2 papers, 2022 to 2023). Inflammation of the colon. "In addition, Mex3a was also upregulated in mouse colitis-associated tumors from the azoxymethane-dextran sulfate sodium (AOM-DSS) model." (PMID 36276637, 2022). "Interestingly, the cell state in the TNFα-treated wt organoids was similar to Mex3a positive cells, Lgr5 positive cells, and colitis cells, but not correlated with label-retaining cells (LRC) or other differentiated cells." (PMID 37845228, 2023).
lentivirus infection (2 papers, 2020 to 2022). Virus diseases caused by the Lentivirus genus. "Western blot results showed that the expression of MEX3A protein in the shMEX3A group was downregulated after lentivirus infection compared with the shCtrl group." (PMID 32140076, 2020). "In addition, we confirmed sufficient lentivirus infection efficacy, effective knockdown of MEX3A mRNA and MEX3A protein levels in infected C666-1 and HONE-1 cells (P < 0.01 or 0.001)." (PMID 35490173, 2022).
thyroid cancer (2 papers, 2021 to 2025). "These authors also identified that CREB1 acts as a downstream effector of the MEX3A gene, highlighting its involvement in the regulatory pathway through which MEX3A influences thyroid cancer progression." (PMID 40722651, 2025). "We found six RBPs (AZGP1, IGF2BP2, MEX3A, NUDT16, NUP153, USB1) independently associated with prognosis of patients with thyroid cancer according to univariate and multivariate Cox proportional hazards regression models." (PMID 33816259, 2021).
triple-negative breast carcinoma (2 papers, 2021 to 2023). An invasive breast carcinoma which is negative for expression of estrogen receptor (ER), progesterone receptor (PR), and human epidermal growth factor receptor 2 (HER2). "In addition, high MEX3A expression is associated with the advanced stage of malignancy and poor prognosis of triple negative breast cancer." (PMID 34486491, 2021). "Generally, upregulation of MEX3A promotes proliferation and migration in triple negative breast cancer via modulating PI3K/AKT signaling." (PMID 34486491, 2021). "Meanwhile, the expression of MEX3A and IGFBP4 correlated with triple-negative breast cancer (TNBC) of the lack of estrogen and progesterone receptors and HER2." (PMID 37433992, 2023).
brain cancer (1 paper, 2020). A primary or metastatic malignant neoplasm affecting the brain. "It is now clear that the stemness property of mex3A, already demonstrated in adult intestinal stem cells and cancer cells, is a key feature of mex3a also in developing brain, opening new lines of investigation to better understand its role during brain aging and brain cancer development." (PMID 33072742, 2020). "In light of this, in the future, it will be interesting to focus on the possible mex3A targets in neuroblast and adult neural stem cells to better clarify its role in development and aging of the CNS with possible translational implications in brain cancer research." (PMID 33072742, 2020).
chronic hepatitis B (1 paper, 2024). "In this study, we examined the link between the methylation state of the Mex3a promoter in patients and other clinicopathological traits using MethyLight to detect the degree of Mex3a promoter methylation in HBV-associated HCC, chronic hepatitis B (CHB), and healthy controls (HCs)." (PMID 39564121, 2024).
colon adenocarcinoma (1 paper, 2022). "Likewise, KEGG analysis ranked WNT signaling pathway second among the enriched terms, while GSEA assay showed positive relationship between MEX3A and WNT activity in colon adenocarcinoma." (PMID 36276637, 2022). "Moreover, upon LinkedOmics analysis of transcriptome profiles of 379 colon adenocarcinomas (COAD) in TCGA, we identified that 6237 genes significantly and positively correlate with MEX3A." (PMID 36276637, 2022).
colorectal tumors (1 paper, 2022). "MEX3A levels were markedly elevated in almost all types of colorectal tumor tissues except rectosigmoid mucinous adenocarcinoma, and they positively correlated with individual cancer stages." (PMID 36276637, 2022). "The biological functions of MEX3A were studied using Mex3a knockout (KO) and intestinal epithelium specific conditional knockout (cKO) mice, AOM-DSS mouse colorectal tumor model, Apc floxed mouse tumor model and intestinal and tumor organoids." (PMID 36276637, 2022). "Immunohistochemical analysis showed that KLF4 is significantly downregulated in human colorectal tumors relative to peritumor tissues, exhibiting negative correlation with MEX3A." (PMID 36276637, 2022).
endometrial cancer (1 paper, 2022). Primary or metastatic malignant neoplasm involving the endometrium (mucous membrane that lines the endometrial cavity). "Recently, MEX3A was reported to be a prognostic biomarker and served as a novel cancer-critical splicing factor in endometrial cancer." (PMID 35715407, 2022). "MEX3A was reported to correlate with RNA splicing in endometrial cancer by analyzing RNA-seq data." (PMID 35715407, 2022).
Failure to thrive (1 paper, 2020). Failure to thrive (FTT) refers to a child whose physical growth is substantially below the norm. "About 40% of them survive until adulthood, whereas the remaining 60% exhibit a general failure to thrive and postnatal lethality associated with prominent alterations in the intestinal tract, pinpointing a primary role for MEX3A in intestinal function." (PMID 32052574, 2020).
gastric tumor (1 paper, 2021). "Up‐regulation of MEX3A in gastric tumor tissues was previously shown to promote cell proliferation and migration, but the mechanism involved was not investigated." (PMID 33159833, 2021).
large cell lung cancer (1 paper, 2023). "MEX3A was expressed in LUAD, LUSC and large cell lung cancer (LCLC); MEX3B was detected in LCLC; and MEX3D was expressed in LUAD." (PMID 36507941, 2023).
microcephaly (1 paper, 2020). A congenital or acquired developmental disorder in which the circumference of the head is smaller than normal for the person's age and sex. "Using gain and loss of gene function approaches, we showed that, in Xenopus embryos, mex3A is required for neuroblast proliferation and its depletion reduced the neuroblast pool, leading to microcephaly." (PMID 33072742, 2020).
Obesity (1 paper, 2022). Accumulation of substantial excess body fat. "The findings could be of special interest for childhood-obesity-induced GBM, as targeting MEX3A as a novel molecular approach can regulate the cytokine production from the adipocytes and immunocytes to prevent the development or progression of GBM in children." (PMID 36295107, 2022). "Out of the known molecular drivers that play a role in obesity-induced GBM, the RIG-I protein and MEX3A could be of potential interest, as they can regulate the cytokines released from the adipocytes and inflammatory cells of an obese person and can regulate the occurrence or development of GBM." (PMID 36295107, 2022).
sarcoma (1 paper, 2024). A usually aggressive malignant neoplasm of the soft tissue or bone. "For this we selected three RBPs which are among the top 20% most elevated in the sarcoma interactomes: IGF2BP3, MEX3A and AKAP1." (PMID 38561347, 2024).
serous ovarian cancer (1 paper, 2022). "This was the first study to evaluate the expression of MEX3A and its relationship with clinical prognosis and parameters using Tissue Microarray of high-grade serous ovarian cancer." (PMID 35715407, 2022).
cancer (34 papers, 2017 to 2026). A tumor composed of atypical neoplastic, often pleomorphic cells that invade other tissues. "Predominantly through the effects it has on proliferation and stemness, MEX3A upregulation is associated with a variety of cancers, including CRC, ovarian, breast, ccRCC, and osteosarcoma." (PMID 41516083, 2025). "Frequency of CD44+ cells and expression levels of Cd44 and other cancer stem cell markers Ascl2, Lgr5 and Smoc2 were markedly reduced in Mex3a-deficient tumors." (PMID 36276637, 2022). "MEX3A is encoded on chromosome 1q22 within a region (1q21-1q25) that is gained in various cancers and encodes several pro-oncogenic genes, e.g., RAB25." (PMID 34067172, 2021). "Chi-square tests were used to analyze clinical variables between the two groups, in which high MEX3A expression was associated with cancer related mortality (p = 0.001)." (PMID 31998552, 2020). "The multivariable Cox model adjusted for the group of mex3a expression level, age, gender, tumor status, and pathological stage showed that only the age and cancer status groups were associated with the overall survival." (PMID 28903380, 2017). "For instance, Mex-3 RNA Binding Family Member A (MEX3A) is strongly associated with cancer." (PMID 36833284, 2023). "Furthermore, recent reports have implicated MEX3A as an oncogene that promotes tumor growth and cancer cell invasion in a variety of cancers such as lung, breast and cervical cancer 20-22." (PMID 36276637, 2022). "Expression of MEX3A is associated with the cancer proliferation and migration in several cancers." (PMID 34486491, 2021). "Studies in recent years have shown that Mex3a may be closely linked to cancer." (PMID 32792503, 2020). "Other studies show that expression of MEX3A correlates to upregulation of Wnt signaling components in several cancers including CRC, HCC, endometrial, and breast." (PMID 41516083, 2025). "As for MEX3A, an increasing body of evidence suggests it promotes tumorigenesis and development in different cancer." (PMID 38914858, 2024). "Previous studies have revealed that MEX-3 RNA binding family members play an important role in cancer development and progression, especially MEX3A." (PMID 38914858, 2024). "To explore the role of the MEX3 family in cancers, we used TCGA for pan-cancer analysis of the expression of MEX3A, MEX3B, MEX3C and MEX3D." (PMID 38914858, 2024). "Mex-3 RNA binding family member A (MEX3A), another RNA-binding protein, has been implicated in cancer regulation." (PMID 38105650, 2023). "To gain insight into the molecular mechanism of how MEX3A regulates stemness and proliferative capacity of both ISCs and cancer cells, we performed genome-wide transcriptome analysis on intestinal crypt cells from control (n = 4) and KO (n = 4) mice." (PMID 36276637, 2022). "Next we asked if MEX3A contributes to radiation therapy resistance, a property attributed to cancer stem cells." (PMID 36276637, 2022). "MEX3A functions as an oncoprotein that retains cancer cells in undifferentiated and proliferative status and it enhances their radioresistance to DNA damage." (PMID 36276637, 2022). "Mechanistically, E2F3-induced MEX3A overexpression sustains cancer cells in a rapidly dividing and undifferentiated state by directly suppressing KLF4, a key pro-differentiation regulator, to activate WNT signaling." (PMID 36276637, 2022). "Recent research shows that MEX3A is highly expressed in a variety of cancers and promotes the occurrence and metastasis of cancer, which is related to the poor prognosis of patients." (PMID 35715407, 2022). "Knockdown of MEX3A with siRNA or addition of KLF4 agonist significantly suppressed tumor growth both by increasing differentiation status of cancer cells and by suppressing their proliferation." (PMID 36276637, 2022). "Bioinformatics analysis of TCGA data previously revealed that MEX3A somatic copy number and expression are upregulated in multiple cancer types." (PMID 35490173, 2022).